THEM4 (thioesterase superfamily member 4)
Description:
Has acyl-CoA thioesterase activity towards medium and long-chain (C14 to C18) fatty acyl-CoA substrates, and probably plays a role in mitochondrial fatty acid metabolism. Plays a role in the apoptotic process, possibly via its regulation of AKT1 activity. According to PubMed:11598301, inhibits AKT1 phosphorylation and activity. According to PubMed:17615157, enhances AKT1 activity by favoring its phosphorylation and translocation to plasma membrane.
Synonyms: CTMP
Tractability: Small molecule: a structure with a bound ligand is known. Antibody: UniProt places it where antibodies can reach, with high confidence; its Gene Ontology location is reachable by antibodies, with high confidence. PROTAC: ubiquitination databases record sites on it; its protein half-life has been measured.
Gene: Protein-coding gene on chromosome 1 (151,870,866 to 151,909,637, reverse strand). Ensembl gene ENSG00000159445.
Subcellular location: Cell membrane; Cell projection, ruffle membrane; Cytoplasm; Mitochondrion; Mitochondrion inner membrane; Mitochondrion intermembrane space
Pathways (Reactome):
Signal Transduction: Activation of AKT2; Negative regulation of the PI3K/AKT network; PIP3 activates AKT signaling; VEGFR2 mediated vascular permeability
Immune System: CD28 dependent PI3K/Akt signaling
Metabolism: Mitochondrial Fatty Acid Beta-Oxidation
Gene Ontology:
Molecular function: long-chain fatty acyl-CoA hydrolase activity; protein binding; medium-chain fatty acyl-CoA hydrolase activity
Biological process: fatty acid metabolic process; negative regulation of phosphatidylinositol 3-kinase/protein kinase B signal transduction; regulation of mitochondrial membrane permeability involved in apoptotic process; lipid metabolic process
Cellular component: cytoplasm; cytosol; mitochondrial intermembrane space; mitochondrion; plasma membrane; mitochondrial matrix; mitochondrial inner membrane; ruffle membrane
Genetic constraint (gnomAD): Loss-of-function variants: 17 observed, 16.18 expected, observed/expected ratio (o/e) 1.05, 90% interval 0.72 to 1.57. The upper end of that interval is the gene's LOEUF score, 1.57, which puts it in group 6 of 6, group 1 being the genes least tolerant of losing a copy. Missense variants: 202 observed, 215.72 expected, observed/expected ratio (o/e) 0.94, 90% interval 0.83 to 1.05. Synonymous variants: 79 observed, 74.46 expected, observed/expected ratio (o/e) 1.06, 90% interval 0.88 to 1.28.
Homologues: Orthologues: chimpanzee THEM4 (97% identical), rat Them4 (67% identical), mouse Them4 (66% identical), guinea pig THEM4 (59% identical), tropical clawed frog THEM4 (48% identical), zebrafish them4 (40% identical). Paralogues in human: THEM5 (35% identical).
Diseases named in the same sentence as THEM4 in open-access papers:
THEM4 is named in the same sentence as 31 diseases in open-access papers, as found by Europe PMC text mining. Sharing a sentence is not in itself a finding about the gene and the disease. The quoted sentences say what the papers report.
Colon Cancer (2 papers, 2021 to 2022). "In the development of colon cancer, tumor-derived exosomes can mediate this process through a variety of ways, such as targeting thioesterase superfamily member 4- (THEM4-) mediated PI3K/AKT and NF-κB pathways, targeting programmed cell death protein 4 (PDCD4)." (PMID 35845138, 2022).
Obesity (2 papers, 2019 to 2021). Accumulation of substantial excess body fat. "Here we show VAT from individuals with obesity to have 1.7-fold higher THEM4 mRNA than lean counterparts." (PMID 31798691, 2019).
depression (1 paper, 2024). "We identified six core genes (GRB10, TDRD9, BCL7A, GPR18, KLRG1, and THEM4) significantly associated with depression and cancer." (PMID 39867577, 2024). "This study conducted a comprehensive bioinformatics analysis, identifying six core genes (BCL7A, GPR18, GRB10, KLRG1, TDRD9, and THEM4) associated with depression and validating their diagnostic value in the context of the disorder." (PMID 39867577, 2024). "The results indicated that BCL7A (AUC: 0.656), GPR18 (AUC: 0.9677), GRB10 (AUC: 0.678), KLRG1 (AUC: 0.661), TDRD9 (AUC: 0.698), and THEM4 (AUC: 0.678) exhibit high diagnostic value for depression." (PMID 39867577, 2024). "Among them, GRB10 and TDRD9 were significantly upregulated, while BCL7A, GPR18, KLRG1, and THEM4 were significantly downregulated in patients with depression." (PMID 39867577, 2024). "We identified six core genes (BCL7A, GPR18, GRB10, KLRG1, TDRD9, and THEM4), confirming their critical value in diagnosing depression." (PMID 39867577, 2024). "These pathways suggest that BCL7A, GPR18, KLRG1, and THEM4 play roles in immune signaling and metabolic pathways, further underscoring their relevance to depression." (PMID 39867577, 2024). "In depression, GRB10 and TDRD9, involved in cell growth and stress responses, exhibited elevated expression, while BCL7A, GPR18, KLRG1, and THEM4, linked to immune regulation and apoptosis, showed reduced expression, suggesting dysregulated cellular signaling and impaired immune function." (PMID 39867577, 2024). "Similarly, BCL7A, GPR18, KLRG1, and THEM4, which are downregulated in depression, also exhibit diverse expression trends across cancers." (PMID 39867577, 2024). "To more accurately predict and assess the progression of depression, we constructed a nomogram model for depression diagnosis based on the core genes (GRB10, TDRD9, BCL7A, GPR18, KLRG1, and THEM4) using the rms package." (PMID 39867577, 2024). "To investigate the correlation between cancer and depression, we examined the expression of BCL7A, GPR18, GRB10, KLRG1, TDRD9, and THEM4 across various cancer types using the TCGA database." (PMID 39867577, 2024). "qPCR results demonstrated that, compared to the normal control group, the expression of GRB10 and TDRD9 was significantly elevated in the blood of depression patients, while the expression of BCL7A, GPR18, KLRG1, and THEM4 was significantly reduced." (PMID 39867577, 2024). "The results showed that the expression levels of GRB10 and TDRD9 were significantly increased in depression patients compared to the control group, while the expression levels of BCL7A, GPR18, KLRG1, and THEM4 were significantly decreased, all with statistical significance." (PMID 39867577, 2024).
Sepsis (1 paper, 2025). Sepsis is defined as life-threatening organ dysfunction caused by a dysregulated host response to infection. "This suggests that THEM4 may play a role in sepsis by regulating phosphorylation." (PMID 40421007, 2025). "Among them, YME1L1, THEM4, and COQ10A showed significantly lower expression levels in sepsis samples, while ECHDC3 exhibited markedly higher expression." (PMID 40421007, 2025). "Four biomarkers (YME1L1, ECHDC3, THEM4, and COQ10A) related to mitochondrial and macrophage polarization in sepsis were obtained by differential expression, machine learning, and expression validation." (PMID 40421007, 2025). "Notably, RT-qPCR analysis confirmed that YME1L1, THEM4, and COQ10A exhibited significantly lower expression levels in sepsis samples." (PMID 40421007, 2025). "Therefore, machine learning and gene expression analysis were utilized in this study to identify YME1L1, ECHDC3, THEM4, and COQ10A as biomarkers for sepsis in our study." (PMID 40421007, 2025). "Subsequent gene expression analysis revealed that YME1L1, THEM4, and COQ10A exhibited significantly lower expression levels in sepsis patient samples from both the GSE95233 and GSE28750 datasets, while ECHDC3 demonstrated markedly higher expression in sepsis patients (p < 0.05)." (PMID 40421007, 2025). "Consequently, YME1L1, THEM4, COQ10A, and ECHDC3 were identified as biomarkers for sepsis." (PMID 40421007, 2025). "RT-qPCR results showed YME1L1, THEM4, and COQ10A were obviously lower expression in sepsis samples (p < 0.05), while ECHDC3 did not significant differences between sepsis and control samples." (PMID 40421007, 2025).
septic shock (1 paper, 2024). Shock caused by infection; frequently caused by gram negative bacteria, although some cases have been caused by other bacteria, viruses, fungi, and protozoa; characterized by fever, chills, tachycardia, tachypnea, and hypotension. "In this study, we recognized four immune-mitochondrial key genes (PGS1, C6orf136, THEM4, and EPHX2) in septic shock and designed a novel gene diagnosis model that provided a new and meaningful way for the diagnosis of septic shock." (PMID 39609718, 2024).
tumor (14 papers, 2009 to 2025). "Conversely, THEM4, TDRD9, and KLRG1, which act as risk factors in some cancers, might contribute to tumor progression through immune evasion mechanisms or by impairing apoptosis pathways." (PMID 39867577, 2024). "For instance, BCL7A and GRB10 showed protective roles in some cancers, possibly through mechanisms such as enhancing immune infiltration or suppressing oncogenic pathways, while THEM4, TDRD9, and KLRG1 acted as risk factors in others, potentially by inhibiting tumor suppressor functions." (PMID 39867577, 2024). "For example, overexpression of GRB10 and TDRD9 may enhance cancer cell proliferation, while downregulation of BCL7A, GPR18, KLRG1, and THEM4 could contribute to reduced immune surveillance and tumor evasion." (PMID 39867577, 2024). "THEM4 reversely regulates phosphatidylinositol 3-kinase (PI3K)/Akt and thus has certain anti-inflammatory and anti-tumor effects." (PMID 34249713, 2021). "Genes such as BCL7A and GRB10 may exert anti-cancer effects by promoting immune cell infiltration, whereas KLRG1, THEM4, and TDRD9 might suppress immune cell infiltration, facilitating tumor progression." (PMID 39867577, 2024).
cancer (10 papers, 2016 to 2025). A tumor composed of atypical neoplastic, often pleomorphic cells that invade other tissues. "Some studies have demonstrated that THEM4 binds to Akt to regulate its phosphorylation on the mechanism of cancers and other diseases." (PMID 40421007, 2025).
THEM4 also shares sentences with these, for which no sentence is quoted: breast carcinoma (3 papers); lung carcinoma (3); amyotrophic lateral sclerosis (2); ischemia (2); liver cancer (2); lymph node metastasis (2); Stroke (2); Brain Infarct (1); cardiovascular disease (1); Cerebral ischemia (1); cervical cancer (1); colorectal cancer (1); diabetes (1); glioblastoma (1); head and neck squamous cell carcinoma (1); hepatocellular carcinoma (1); hyperthyroidism (1); infection (1); ischemic stroke (1); metastatic melanoma (1); nasopharyngeal carcinoma (1); pancreatic cancer (1); triple-negative breast carcinoma (1); viral infection (1).